RN7SL237P (RNA, 7SL, cytoplasmic 237, pseudogene)
Gene: Miscellaneous RNA gene on chromosome 20 (38,098,414 to 38,098,700, reverse strand). Ensembl gene ENSG00000264767.
Homologues: Orthologues: chimpanzee Metazoa_SRP (99% identical). Paralogues in human: RN7SL2 (78% identical), RN7SL1 (77% identical), RN7SL187P (77% identical), RN7SL3 (77% identical), RN7SL130P (76% identical), RN7SL218P (76% identical), RN7SL448P (76% identical), RN7SL709P (76% identical), RN7SL408P (76% identical), RN7SL18P (75% identical), RN7SL464P (75% identical), RN7SL479P (75% identical), and 703 more.